METTL1 (methyltransferase 1, tRNA methylguanosine)
Diseases named in the same sentence as METTL1 in open-access papers (continued):
Sharing a sentence is not in itself a finding about the gene and the disease.
myocardial infarction (3 papers, 2024 to 2026). Gross necrosis of the myocardium, as a result of interruption of the blood supply to the area, as in coronary thrombosis. "METTL1 and m7G tRNA modification were upregulated in mice with I/R injury hearts and the plasma of patients with acute myocardial infarction." (PMID 41510184, 2026). "In cardiovascular diseases, fibroblast‐specific deletion of METTL1 notably alleviated the myocardial infarction‐induced cardiac fibrosis by enhancing α‐SMA, col1, and col3 mRNA translation efficiency." (PMID 41510184, 2026).
non-small cell lung carcinoma (3 papers, 2019 to 2026). A group of at least three distinct histological types of lung cancer, including non-small cell squamous cell carcinoma, adenocarcinoma, and large cell carcinoma. "METTL1 has also been implicated in resistance to EGFR tyrosine kinase inhibitors (EGFR-TKIs), a major clinical challenge in non-small cell lung cancer (NSCLC) despite durable complete responses in some patients." (PMID 41562049, 2025).
ovarian carcinoma (3 papers, 2019 to 2023). A malignant neoplasm originating from the surface ovarian epithelium. "This study identified four-DERRG signature (ALYREF, ZC3H13, WTAP, and METTL1) in OC, which was an independent prognostic model for patient stratification, prognostic evaluation, and prediction of response to immunotherapy in ovarian cancer by classifying OC patients into high- and low-risk groups." (PMID 36545327, 2022).
ovarian serous cystadenocarcinoma (3 papers, 2021 to 2025). A malignant serous cystic epithelial neoplasm arising from the ovary. "METTL1 is associated with a poor prognosis in KIRC and mesothelioma patients, while it is related to favorable survival in patients with ovarian serous cystadenocarcinoma." (PMID 35590385, 2022). "In addition, METTL1 expression is associated with extremely poor prognosis in KIRC and mesothelioma, while it is related to superior survival in patients with ovarian serous cystadenocarcinoma." (PMID 35590385, 2022). "Furthermore, the survival curve analysis indicated a significant relationship between the expression of METTL1 and OS and DSS of patients with KIRC, LGG, LIHC, mesothelioma, ovarian serous cystadenocarcinoma, and PCPG." (PMID 34838021, 2021).
prostate tumour (3 papers, 2023 to 2025). "Here, we show that the transfer RNA N7-methylguanosine (m7G) transferase METTL1 is highly expressed in primary and advanced prostate tumours." (PMID 37516825, 2023). "Analysis of fluorescence-activated cell sorting (FACS)-sorted cells confirmed higher Mettl1 expression in Sca1low/CD49flow/CD24high luminal cells within prostate tumours, which have been identified as the preferred cell-of-origin in most lineage-tracing and organoid studies." (PMID 37660182, 2023).
Cognitive impairment (2 papers, 2023 to 2025). Abnormal cognition is characterized by deficits in thinking, reasoning, or remembering. "Our findings further reveals that mice with hippocampal Mettl1 deficiency displays decreased neurogenesis and cognitive impairment, whereas ectopic overexpression of Mettl1 improves neurogenesis and cognition in mouse models of AD." (PMID 37779199, 2023). "Altogether, current results highlight the novel function that targeting Mettl1 in promoting neurogenesis alleviates cognitive impairment of AD." (PMID 37779199, 2023). "In addition, METTL1 knockdown reduces hippocampal neurogenesis and spatial memory, whereas METTL1 overexpression rescues defective neurogenesis and cognitive impairment in adult mice." (PMID 39979979, 2025). "Hippocampal neurogenesis is closely associated with cognitive function, we hypothesized that decreased neurogenesis in Mettl1-deficency mice might induce cognitive impairment." (PMID 37779199, 2023). "As Mettl1-deficency mice exhibited decreased neurogenesis and cognitive impairment, we next investigated whether forced expression of Mettl1 improved hippocampal neurogenesis and cognitive function in APP/PS1 mice." (PMID 37779199, 2023). "Additionally, forced expression of Mettl1 remarkably ameliorated cognitive impairment in APP/PS1 mice." (PMID 37779199, 2023).
colorectal adenocarcinoma (2 papers, 2021 to 2025). The most common type of colorectal carcinoma.
neuroblastoma (2 papers, 2022 to 2024). Neuroblastoma (NB) is the most common solid, extracranial childhood tumor. "METTL1 is significantly upregulated in advanced neuroblastoma, knockdown of METTL1 would result in a significant increase in apoptosis of neuroblastoma cells." (PMID 39289775, 2024). "We found that METTL1 highly expressed in high risk NBL based on the Children’s Oncology Group (COG), advanced NBL according to the International Neuroblastoma Staging System (INSS), and NBL with MYCN amplification." (PMID 36071474, 2022). "The results of this study enrich the network of epigenetics in the regulation of neuroblastoma progression, and METTL1 is expected to provide new biomarkers and novel therapeutic targets for the diagnosis of NBL, significantly advanced NBL." (PMID 36071474, 2022).
Pan (2 papers, 2021 to 2022). "We found that, similar to the TCGA Pan-Cancer cohort, at least ten METTLs (e.g. METTL1, METTL2A, METTL2B, EEF1AKNMT) showed high-level amplifications in more than 2% of CCLE lines." (PMID 34285249, 2021).
peripheral arterial disease (2 papers, 2021 to 2022). A disorder of the arteries supplying the upper and lower extremity and the visceral organs. "Our findings emphasize a critical link between mRNA m7G and ischemia and provide a novel insight of targeting METTL1 in the therapeutic angiogenesis for ischemic disorders, including peripheral arterial disease." (PMID 34136476, 2021). "As a consequence, the METTL1 could be considered as a potentially innovative therapeutic target in peripheral arterial disease (PAD) in clinical treatment." (PMID 35937999, 2022).
psoriasis (2 papers, 2023 to 2026). An autoimmune condition characterized by red, well-delineated plaques with silvery scales that are usually on the extensor surfaces and scalp. "Collectively, these data establish that METTL1 modulates psoriasis by fostering p38-dependent chemokine production and neutrophil recruitment, identifying the METTL1-BDKRB1 axis as a novel therapeutic target." (PMID 42261843, 2026).
teratoma (2 papers, 2020 to 2025). A non-seminomatous germ cell tumor characterized by the presence of various tissues which correspond to the different germinal layers (endoderm, mesoderm, and ectoderm). "Teratoma formation was observed at 6 weeks post-injection; we observed that METTL1-KD-derived teratomas had a significantly increased volume and weight compared to control teratomas." (PMID 32698871, 2020). "Most importantly, compared with control hiPSCs, METTL1-KD hiPSCs significantly enhance teratoma formation in vivo by promoting cell proliferation and angiogenesis in nude mice." (PMID 32698871, 2020).
basal cell carcinoma (1 paper, 2025). A carcinoma involving the basal cells. "However, further validation is needed to determine the expression and impact of METTL1 on cutaneous basal cell carcinoma, which is the most common skin cancer and is characterized by relatively low levels of malignancy." (PMID 39870616, 2025).
benign prostatic hyperplasia (1 paper, 2023). A non-cancerous nodular enlargement of the prostate gland. "Increased expression of METTL1 was confirmed in PCa-derived cell lines compared to immortalised benign prostatic hyperplasia or prostatic epithelium-derived cell lines." (PMID 37516825, 2023).
bladder tumour (1 paper, 2021). "We further determined METTL1 protein expression in human bladder tumour specimens using IHC." (PMID 34936728, 2021).
brain malformations (1 paper, 2025). "In the case of METTL1, missense mutations have been linked to diseases such as primary dwarfism and brain malformations, suggesting that these mutations could affect tRNA m7G methylation and, as a result, translation efficiency." (PMID 40018039, 2025).
Cardiac Ischemia (1 paper, 2026). "Nevertheless, there is still a lack of understanding regarding the roles and molecular mechanisms underlying the METTL1‐mediated m7G tRNA modification in cardiac ischemia/reperfusion (I/R) injury." (PMID 41510184, 2026).
ciliopathy (1 paper, 2024). A genetic disorder of the cellular cilia or the cilia anchoring structures, the basal bodies, or of ciliary function. "Because of these unanticipated findings, we questioned the importance of the functional interaction of WDR4 with METTL1 regarding the ciliopathy-like phenotypes in fish and cells." (PMID 39251572, 2024).
cognitive decline (1 paper, 2023). "To address this possibility, we employed Morris water maze to assess spatial learning and memory of the mice and found that Mettl1-deficency mice showed a markedly cognitive decline during the last one session in the acquisition trial, implying an impaired learning ability." (PMID 37779199, 2023).
cold (1 paper, 2023). "Our results show that the typical m7G methylation-related genes, METTL1, and WDR4, are more highly expressed in high-risk and cold tumors compared to the other two subgroups." (PMID 37147395, 2023).
colitis (1 paper, 2026). Inflammation of the colon. "In vivo, inhibition of the METTL1/m7G/SLC7A11 axis exacerbates chronic DSS-induced colitis but alleviates acute DSS-induced colitis, revealing a switch from adaptive to maladaptive signaling with escalating metabolic stress." (PMID 42212324, 2026).
cystitis (1 paper, 2021). Inflammation of the urinary bladder. "METTL1 was upregulated in NMIBC samples relative to cystitis tissue." (PMID 34936728, 2021). "Weak METTL1 expression was observed in the majority of human cystitis tissue samples analysed." (PMID 34936728, 2021).
deafness (1 paper, 2022). An inherited or acquired condition characterized by the complete loss of the ability to hear from one or both ears. "Genes already associated with hearing or deafness (mouse and/or zebrafish) were selected as controls/references for comparison and validation of the candidate genes’ results: Eya4 (DFNA10), Gsdmea (DFNA5), Gsdmeb (DFNA5), Pou4f1, Elavl4, Sclla3a, Gab1 (DFNB26), and Mettl1 (DFNM)." (PMID 36553541, 2022).
Down syndrome (1 paper, 2025). "WDR4, a functional methyltransferase in m7G methylation complex with METTL1, is frequently associated with neurodevelopmental disorders, including microcephalic primordial dwarfism and Down syndrome." (PMID 41149057, 2025).
epilepsy (1 paper, 2025). A brain disorder characterized by episodes of abnormally increased neuronal discharge resulting in transient episodes of sensory or motor neurological dysfunction, or psychic dysfunction. "In this work, we screened five key m7G regulators in epilepsy and created a nomogram based on them to predict the risk of epilepsy, including METTL1, NUDT3, EIF4E3, LSM1, and SNUPN." (PMID 40658715, 2025). "Gene expression analysis of datasets GSE143272 and GSE190452 identified 8 differentially expressed m7G regulators (NUDT3, EIF4E3, LARP1, IFIT5, SNUPN, METTL1, EIF4A1, and LSM1) in epilepsy." (PMID 40658715, 2025). "The boxplot revealed that epilepsy patients had up-regulated expression levels of NUDT3, EIF4E3, LARP1, IFIT5, and SNUPN, and down-regulated expression levels of METTL1, EIF4A1, and LSM1." (PMID 40658715, 2025).
Fanconi anemia (1 paper, 2024). Fanconi anemia (FA) is a hereditary DNA repair disorder characterized by progressive pancytopenia with bone marrow failure, variable congenital malformations and predisposition to develop hematological or solid tumors.
fibrosis (1 paper, 2024). the formation of excess fibrous connective tissue in an organ or tissue in a reparative or reactive process. "Furthermore, Mettl1 overexpression induced cardiac fibrosis, as demonstrated by Masson's staining, along with a remarkable increase in mRNA expression of fibrotic genes, as well as increased protein levels of Col1a1 and α‐SMA." (PMID 38810124, 2024).
giant cell tumor (1 paper, 2024). A benign, intermediate, or malignant tumor that arises from the bone or soft tissue. "The m7G methyltransferase METTL1 is negatively correlated with M2 and M0 macrophages in tenosynovial giant cell tumors, suggesting that METTL1 may induce M1 polarization of macrophages in tenosynovial giant cell tumors." (PMID 39372415, 2024).
ischemia (1 paper, 2021). A hypoperfusion of the BLOOD through an organ or tissue caused by a PATHOLOGIC CONSTRICTION or obstruction of its BLOOD VESSELS, or an absence of BLOOD CIRCULATION. "Phenotypes of improved blood flow recovery and increased angiogenesis with enhanced m7G methylation in mRNA upon METTL1 overexpression post-ischemia were obtained." (PMID 34136476, 2021). "In addition, the Laser Doppler showed significantly enhanced blood flow recovery and accompanied by an increased capillary density (CD31 positive) as well as increased small artery density (a-SMA positive) upon METTL1 overexpression post-ischemia." (PMID 34136476, 2021).
lentivirus infection (1 paper, 2024). Virus diseases caused by the Lentivirus genus. "Subsequently, METTL1-specific shRNA was utilized to silence the gene through lentivirus infection." (PMID 38693422, 2024).
leukemia (1 paper, 2023). A malignant (clonal) hematologic disorder, involving hematopoietic stem cells and characterized by the presence of primitive or atypical myeloid or lymphoid cells in the bone marrow and the blood. "Besides, stable knockdown of METTL1 could effectively inhibit the growth of leukemia stem cells." (PMID 37679400, 2023).
lipid metabolic disorders (1 paper, 2026). "Inhibition of NAMPT reversed the protective effects of METTL1-deficient MSCs against MASLD-related lipid metabolic disorders." (PMID 41903937, 2026).
lymph node metastasis (1 paper, 2025). "Both METTL1 and WDR4 levels were positively correlated with lymph node metastasis in PTC patients." (PMID 40360483, 2025). "By analyzing the protein expression of METTL1, WDR4, and TNF-α in PTC tumor tissues, we found that PTC tissues from patients with lymph node metastasis had higher METTL1, WDR4, and TNF-α expression than those from patients without lymph node metastasis did." (PMID 40360483, 2025).
malignant glioma (1 paper, 2021). A grade III or grade IV glioma arising from the central nervous system. "In addition, according to the analysis results of antitumor drugs, 5-fluoro-deoxy-uridine and hydroxyurea have a strong correlation with METTL1, and studies have shown that combination chemotherapy with hydroxyurea and other drugs has a certain therapeutic effect on malignant glioma." (PMID 34838021, 2021).
Miscarriage (1 paper, 2026). A pregnancy that ends at a stage in which the fetus is incapable of surviving on its own, defined as the spontaneous loss of a fetus before the 22th week of pregnancy. "In this study, based on two UM case-control groups, four ZnCl2-exposed mouse models, and a ZnCl2-exposed trophoblast Swan 71 cell model, we obtain a consistent conclusion that excessive Zn exposure causes disulfidptosis and thus induces miscarriage by up-regulating the GATA1/METTL1/SLC7A11 axis." (PMID 42095470, 2026). "Knockdown of murine Slc7a11, Gata1, or Mettl1, or supplement with NADPH suppresses mouse placental disulfidptosis and alleviates mouse miscarriage." (PMID 42095470, 2026).
Obesity (1 paper, 2025). Accumulation of substantial excess body fat. "In all, the tRNA m7G methyltransferase complex protein METTL1/WDR4 were downregulated in HFD-induced obesity mice." (PMID 41292047, 2025).
oral squamous cell carcinoma (1 paper, 2025). "A recent study related to oral squamous cell carcinoma pointed out that, as the main m7G writer, METTL1 could stimulate oxidative phosphorylation through m7G tRNA modification causally." (PMID 40658715, 2025).
papillary thyroid cancer (1 paper, 2025). "However, the biological function of METTL1-mediated m7G tRNA modification in papillary thyroid cancer (PTC) is unclear." (PMID 40360483, 2025).
paraganglioma (1 paper, 2021). A benign or malignant neoplasm arising from paraganglia located along the sympathetic or parasympathetic nerves. "In contrast, METTL1 expression was found to be significantly lower in pheochromocytoma and paraganglioma (PCPG) than in the corresponding normal tissue." (PMID 34838021, 2021).
rectal cancer (1 paper, 2025). A primary or metastatic malignant neoplasm that affects the rectum. "METTL1 expression was moderate in normal rectal tissues and high in rectal cancer tissues." (PMID 40770782, 2025). "METTL1 expression was low in normal rectal tissues and moderate in rectal cancer tissues." (PMID 40770782, 2025).
Rubinstein-Taybi syndrome (1 paper, 2024). A rare malformation syndrome characterized by congenital anomalies (microcephaly, specific facial characteristics, broad thumbs and halluces and postnatal growth retardation), short stature, intellectual disability and behavioral characteristics. "METTL1 gene polymorphism is associated with neuroblastoma and Rubinstein-Taybi syndrome (RSTS)." (PMID 39155349, 2024).
Sepsis (1 paper, 2025). Sepsis is defined as life-threatening organ dysfunction caused by a dysregulated host response to infection. "This enhancement in stability and expression level of METTL1 further exacerbates the renal damage caused by sepsis." (PMID 40989844, 2025). "The findings reveal that in a sepsis model, the expression of METTL1 is significantly upregulated, promoting pyroptosis in renal tubular epithelial cells." (PMID 40989844, 2025).
serous ovarian cancer (1 paper, 2025). "This study explored the impact of vaginal microbes, metabolites, and METTL1-mediated m7G modification of BRCA1 mRNA on High-Grade Serous Ovarian Cancer (HGSOC)." (PMID 41430564, 2025).
small cell lung carcinoma (1 paper, 2022). Small cell lung cancer (SCLC) is a highly aggressive malignant neoplasm, accounting for 10-15% of lung cancer cases, characterized byrapid growth, and early metastasis. "These altered genes concerned “PI3K-Akt signaling pathway”, “transcriptional misregulation in cancer”, and “small cell lung cancer”, suggesting the significant regulation role of METTL1 in BCa." (PMID 36396627, 2022).
systemic lupus erythematosus (1 paper, 2025). An autoimmune multi-organ disease typically associated with vasculopathy and autoantibody production. "In systemic lupus erythematosus (SLE), lysosomal‐associated membrane protein 3, the CD83 molecule (CD83) and programmed cell death 1 ligand 2 may be downstream targets of METTL1 and are involved in abnormal immunological responses." (PMID 39979979, 2025).
viral infection (1 paper, 2023). "Recent intensive studies on RNA modification have shown that RNA methylation modifications exert a wide range of critical functions, ranging from early development and viral infection to cancer.METTL1 andWDR4 are m7G modification regulators." (PMID 36810782, 2023).